C3orf22 (chromosome 3 open reading frame 22)
Synonyms: MGC34728
Tractability: No criterion of Open Targets' tractability assessment is met for any kind of drug.
Gene: Protein-coding gene on chromosome 3 (126,526,999 to 126,558,965, reverse strand). Ensembl gene ENSG00000180697.
Subcellular location: Cytoplasm
Gene Ontology:
Cellular component: cytoplasm
Genetic constraint (gnomAD): Loss-of-function variants: 7 observed, 11.27 expected, observed/expected ratio (o/e) 0.62, 90% interval 0.35 to 1.17. The upper end of that interval is the gene's LOEUF score, 1.17, which puts it in group 5 of 6, group 1 being the genes least tolerant of losing a copy. Missense variants: 173 observed, 184.56 expected, observed/expected ratio (o/e) 0.94, 90% interval 0.83 to 1.06. Synonymous variants: 79 observed, 83.32 expected, observed/expected ratio (o/e) 0.95, 90% interval 0.79 to 1.14.
Homologues: Orthologues: chimpanzee C3H3orf22 (98% identical), macaque C2H3orf22 (83% identical), dog C3orf22 (52% identical), rat C4h3orf22 (44% identical), mouse BC048671 (43% identical).